ENSG00000293664 (novel transcript)
Gene: Long non-coding RNA gene on chromosome 8 (41,828,264 to 41,832,786, forward strand). Ensembl gene ENSG00000293664.
Gene Ontology:
Biological process: SRP-dependent cotranslational protein targeting to membrane, signal sequence recognition
Cellular component: signal recognition particle, endoplasmic reticulum targeting